UCP1 (uncoupling protein 1)
Diseases named in the same sentence as UCP1 in open-access papers (continued):
Sharing a sentence is not in itself a finding about the gene and the disease.
Obesity (continued). "At gene expression level, UCP1, mainly expressed on brown adipose tissue (BAT) and brown-like beige cells, upregulates thermogenesis and energy expenditure and therefore protect mice from obesity." (PMID 36781473, 2023). "Notably, dietary selenium supplementation elevated its incorporation at the Cys235 of UCP1 protein, which resulted in elevated BAT energy expenditure and resistance to HFD-induced obesity in mice." (PMID 36674862, 2023). "Thus, overexpression of APOA4 in the small intestine and maintenance of elevated levels of plasma APOA4 appear to correlate with elevation of UCP1-dependent BAT thermogenesis and subsequent protection against HFD-induced obesity in mice." (PMID 36835642, 2023). "Supplemental HRW’s thermogenic effects could augment traditional obesity treatment, with HRW-mediated UCP1 upregulation stimulating whole-body energy expenditure and possibly regulating lipid status." (PMID 37259294, 2023). "Although the data compiled above would seem to support the concept of diet-induced thermogenesis and the obesity-promoting consequences of its absence in UCP1 KO mice, there are published data that do not accord with this." (PMID 37661736, 2023). "Taking into consideration the role of UCP1 in BAT thermogenesis as well as in increasing energy expenditure, it is postulated that its activity might be related to obesity." (PMID 37107547, 2023). "From the compilation in that paper, it is clear that the groups of L. P. Kozak and of Martin Klingenspor consistently report an absence of obesity-inducing effects of UCP1 KO, even in mice at thermoneutrality and given a high-fat diet." (PMID 37661736, 2023). "How prolonged time/high age can unmask a potential obesity-inducing effect of UCP1 ablation even in mice living below thermoneutrality is not presently understood." (PMID 37661736, 2023). "In the absence of UCP1, there will still be no ‘unused energy’ to be stored, resulting in no obesity development in the UCP1 KO mice under these conditions." (PMID 37661736, 2023). "These experiments were performed with different mouse strains, given different diets, etc., but in none of the cohorts was an obesity-promoting effect of UCP1 ablation seen." (PMID 37661736, 2023). "If this does not happen, or if UCP1 and brown adipose tissue in any other way are less effective, obesity would develop." (PMID 37661736, 2023). "When given a high-fat diet, the UCP1 KO mice became clearly more obese than the wild-type mice —although they did not develop the massive obesity seen in ob/ob mice." (PMID 37661736, 2023). "To investigate the anti-obesity mechanism of PD, we examined the expression of thermogenic proteins PRDM16 and UCP1, mitochondrial biosynthesis-related protein PGC-1α, TFAM and cAMP pathway related protein P-CREB in adipose tissue after (20R)-panaxadiol administration." (PMID 36909162, 2023). "The present study demonstrates that even if such an endpoint is achieved, the augmented amounts of UCP1 can be without anti-obesity function." (PMID 37499977, 2023). "Soon after, it was proposed that thermoneutral housing was required to reveal the effect of UCP1 on mitigating obesity;31 however, independent studies have now demonstrated that obesity is not potentiated in germline Ucp1−/− mice at thermoneutrality." (PMID 37736043, 2023). "Following the concepts above, the prediction would be that the absence of UCP1 in itself should lead to overt obesity, similarly to the obesity-inducing effect of the absence of leptin in the ob/ob mouse." (PMID 37661736, 2023). "A spontaneously occurring UCP1 KO has so far not been examined for obesity on a high-fat diet at thermoneutrality." (PMID 37661736, 2023). "In contrast, current methods to assess thermogenic human fat use in vivo imaging or in vitro techniques and focus on adult patients with obesity, without defining the precise anatomical distribution and ontogeny of UCP1-expressing fat." (PMID 38069028, 2023).
Obesity (continued). "Additionally, uncoupling protein-1 (UCP-1) is a member of the uncoupling protein family involved in thermogenesis, energy metabolism, and obesity." (PMID 36771240, 2023). "The mechanism by which BJ reduces obesity may be partly due to its inhibitory effects on the expression of TBK1 and IKKε, and may occur through two different pathways: the TBK1/AMPK/UCP1 pathway and the IKKε/adrenergic/cAMP pathway." (PMID 35962183, 2022). "Moreover, it upregulated the expression of brown fat markers including PR domain containing 16 (PRDM16), uncoupling protein 1 (UCP1), and PPARγ coactivator-1 (PGC-1α), which reduced obesity and restored metabolic homeostasis by altering brown fat phenotype." (PMID 35082907, 2022). "In rodent models of obesity, the activation of BAT and uncoupling protein (UCP1)-positive beige adipocytes in white adipose tissue (WAT) by cold exposure and sympathomimetics (i.e., β3-agonists) can attenuate or reverse obesity, diabetes and atherosclerosis, thus improving metabolic health." (PMID 35163791, 2022). "Furthermore, brown to white transdifferentiation, which was regulated by PGC-1α and UCP-1, is another important contributor to decreased BAT thermogenesis and obesity pathology." (PMID 35365730, 2022). "It has been shown that the depletion of UCP1 triggers severe inflammation and pathological conditions in the liver but not obesity and changes in systemic energy expenditure." (PMID 35982903, 2022). "In summary, UCP1 per se does not protect mice from diet-induced obesity under physiological conditions, irrespective of the type of diet or the ambient temperature." (PMID 35269549, 2022). "Consequently, deletion of GPR30 enhances subcutaneous WAT-isolated SVF differentiating to beige adipocytes and activates the thermogenic beiging program through up-regulation of UCP-1, which thereby protects female mice from HFD-induced obesity." (PMID 35592783, 2022). "Thus, NHDC and GNHDC exerted an anti-obesity effect by increasing fat browning through the regulation of AMPK targets such as PGC-1 α, PRDM16, and UCP1." (PMID 35268062, 2022). "The phenomenon of increased FGF21 levels and resistance to diet induced obesity in UCP1 KO mice is only seen at mild cold, not thermoneutral conditions." (PMID 36034414, 2022). "On the other hand, it has been reported that the inactivation of UCP1 did not potentiate diet-induced obesity in mice." (PMID 36012714, 2022). "In particular, UCP1, a main factor of BAT, defends against cold and obesity." (PMID 35276805, 2022). "Accordingly, in animal models of obesity, the addition of resveratrol could reverse HFD-induced suppression of UCP1 expression and oxygen consumption in BAT, resulting in an increased basic metabolic rate." (PMID 36012714, 2022). "Among the factors that can promote BAT dysfunction in obesity is the reduction of vascularization and, consequently, the β-adrenergic activation pathway that regulates the BAT activity, favoring Ucp1 expression, and stimulates the lipolytic pathway to mobilize fatty acids for oxidation." (PMID 36140428, 2022). "Thus, UCP1 is the best-characterized marker of the WAT browning process and is a good indicator to evaluate possible anti-obesity effects of chemicals or natural products." (PMID 34646848, 2021). "Energy dissipation via UCP1 of BAT potentially enhances the total energy expenditure of the whole body up to 20%; therefore, UCP1 activation is considered a potentially promising therapeutic approach for obesity and diabetes treatment." (PMID 34445344, 2021). "Thus, E2F1 knockout in WAT repressed the autophagy to up-regulate UCP-1 expression and promote WAT browning, which was expected to be used for fat burning to dissipate extra energy and obesity prevention." (PMID 34819874, 2021). "The mechanisms related to UCP-1 in beiging, or BLA, may be major mechanisms with which to prevent obesity." (PMID 34064531, 2021).
Obesity (continued). "Since previous studies have shown that galectin‐1 and galectin‐3 play important roles in obesity and interact with CD146 in the endothelium, we examined whether these proteins regulated UCP1 expression in BAT." (PMID 33747748, 2021). "Melatonin controls obesity and improves glucose homeostasis in rodents, mainly via the thermogenic effects of increasing the amount of brown adipose tissue (BAT) and increases in mitochondrial mass, amount of UCP1 protein, and thermogenic capacity." (PMID 34573114, 2021). "We hypothesize that environmental toxicants commonly used as food additives or pesticides might reduce BAT thermogenesis through suppression of uncoupling protein 1 (UCP1) and this may contribute to the development of obesity." (PMID 34453052, 2021). "One recent study showed that mice lacking Map2k6 were protected against HF‐induced obesity, possibly due to increased energy expenditure and higher Ucp1 expression in adipose tissue." (PMID 33417276, 2021). "Previous studies have shown that the omega-3 polyunsaturated fatty acid, eicosapentaenoic acid (EPA), ameliorates obesity in high-fat (HF) fed male, C57Bl/6 mice at thermoneutral conditions, independent of uncoupling protein 1 (UCP1)." (PMID 34829779, 2021). "In the present study, we observed that hAMSCs-CM promoted UCP1 expression in BAT, indicating that the anti-obesity of hAMSCs-CM might be partially related to their promoting energy expenditure." (PMID 34174964, 2021). "To evaluate whether the PHA would prevent obesity by increasing BAT activity, we assessed the effects of PHA on obesity in UCP-1 KO mice." (PMID 33983894, 2021). "The known anti-obesity effect of functional BAT has drawn research and attention to the activation and regulation mechanism of brown fat functioning, and the specific expression of Ucp1 by BAT has become a hot topic for scientists." (PMID 34943089, 2021). "For those reasons, UCP1, UCP2, and UCP3 may be involved in the development of obesity, T2DM, and diabetic complications." (PMID 34712730, 2021). "In addition to lipolysis related genes, the genes involved in thermogenesis and adipose “browning” process such as PPARs, UCP-1 and PRDM also play important roles in anti-obesity." (PMID 34707567, 2021). "The increase in UCP-1-mediated thermogenesis in BAT has been commonly reported as a compensatory mechanism to increase energy expenditure and prevent diet-induced obesity, although the increases in the expression have been reported to be very variable in magnitude." (PMID 34502170, 2021). "Based on CMAP database, we then used the signature to identify small compounds which could upregulate the UCP1 expression and enhanced activity in adipose (BAT and WAT), and thereby offer a treatment for obesity." (PMID 32190098, 2020). "It has been stressed that cytochrome c oxidase activation associated stimulation of TAG/FA cycle and increased energy expenditure is the core mechanism supporting resistance to obesity in case of complete absence of UCP-1." (PMID 32595696, 2020). "Collectively, this study characterizes the effects of endogenous FGF21 that acts as master regulator to protect from diet-induced obesity in the absence of UCP1." (PMID 32005798, 2020). "Of note, the transgenic overexpression of PRDM16 is still able to protect mice from diet-induced obesity in the absence of UCP1." (PMID 32351446, 2020). "Consistent with our observations, many studies have reported that accumulation of body fat and obesity can be induced by mitochondrial dysfunction related impaired energy expenditure independent of UCP1." (PMID 32595696, 2020). "Collectively, endogenous FGF21-signaling is an interesting therapeutic target, as it appears sufficient to prevent obesity in the absence of UCP1." (PMID 32005798, 2020). "UCP1-ablated mice exposed to mild cold stress but not thermos-neutral temperature kept their ability to overcome obesity." (PMID 32595696, 2020).
Obesity (continued). "In conclusion, intrauterine exposure to low-dose DBP could induce ER stress, which inhibits the expression of UCP1, thereby decreasing the energy consumption by BAT, and affecting the metabolism of lipids and sugars, eventually leading to obesity in offspring." (PMID 33004990, 2020). "Previously, it was shown that whole-body Ahr knockout mice on HFD have increased transcript levels of the thermogenic uncoupling gene Ucp1 in BAT as compared wild type mice, potentially explaining how Ahr knockout could protect against HFD induced obesity." (PMID 32730300, 2020). "Indeed, an opposite trend was observed for S100b (induced by obesity in mouse BAT), and for Ucp1, at this stage upon HFD feeding." (PMID 33101212, 2020). "Subsequent investigations under Ta conditions showed that Ucp1−/− mice were very susceptible to hypothermia, due to recurrent tremors, but did not demonstrate the role of UCP1 in thermogenesis, nor a propensity to develop obesity." (PMID 32012991, 2020). "In terms of maintaining proper balance between energy intake and expenditure, dissipating extra energy for thermogenesis by uncoupling protein 1 (UCP1) without diminishing energy intake is an attractive strategy for anti-obesity treatment." (PMID 32046061, 2020). "UCP-1 plays a key role in thermogenesis through BAT-mediated adaptive non-shivering and the activation of UCP-1 in WAT can promote beigeing to prevent diet-induced obesity." (PMID 30890905, 2019). "Indeed, UCP1 expression in VAT and SAT (UCP1-VAT and UCP1-SAT), particularly in patients with severe obesity, are still controversial." (PMID 31440209, 2019). "Brown and beige adipocytes, with high levels of uncoupling protein 1 (UCP1) expression, could burn lipid to heat and combat obesity." (PMID 30318987, 2019). "We show that, similarly to what is the case in C57Bl/6 mice, diet-induced thermogenesis is mediated solely by BAT UCP1 in the 129s mice and that even in these mice obesity is augmented in the absence of UCP1." (PMID 30807213, 2019). "Although UCP1 was substantially upregulated even in the absence of H. polygyrus as obesity proceeded, infection with H. polygyrus induced significantly more UCP1 expression." (PMID 30962398, 2019). "Here, we show that obesity induced by ERα ablation does not significantly increase BAT UCP1, yet HFD-induced obesity did induce BAT UCP1 both in WT and ERαKO mice." (PMID 30804793, 2019). "UCP1 is found in brown adipose tissue and represents a crucial factor in thermogenesis, which is heat production contributing to the reduction of WAT and physiological defense against obesity." (PMID 31137922, 2019). "Our findings suggest that, despite mitochondrial degeneration described in IR state, UCP1 expression in VAT could contribute to energy expenditure and counteract further weight gain in patients with severe obesity." (PMID 31440209, 2019). "Uncoupling protein 1 (UCP1), which is specifically expressed in BAT, plays an important role in energy expenditure, and promoting its expression could reduce obesity and metabolic dysfunction." (PMID 29522452, 2018). "Cold-sensitive mice lacking UCP1 are not more obesity prone than wild type mice when fed a high fat diet and kept at 21°C." (PMID 30631281, 2018). "In conclusion, DBT could stimulate phosphorylation of AMPK to raise expression of UCP1 and PGC-1α, and activate thermogenesis to prevent obesity." (PMID 30258363, 2018). "The role of UCP1 in BAT is known to be a significant component of the regulatory system governing whole-body energy expenditure, and the protein is thought to be important in preventing the development of obesity." (PMID 29329235, 2018). "Studies in animals lacking BAT or uncoupling protein 1 (UCP1) have clearly demonstrated the involvement of BAT thermogenesis in the protection against diet-induced obesity (DIO)." (PMID 29601492, 2018).
Obesity (continued). "In visceral fat and sWAT from individuals with obesity and those without obesity, we found that expression of Mapk14 correlated positively with the levels of Ucp1." (PMID 29979672, 2018). "Overall, we postulate the following hypothesis: in the course of obesity, secreted factors liberated by obese adipose tissue inhibit FNDC5 and UCP1 expression of differentiating pre-adipocytes promoting enhanced adipogenesis and increasing lipid accumulation." (PMID 29176631, 2017). "Thirdly, ablation of either Ucp1 or Mfn2 changes the overall metabolic response to diet‐induced obesity in the absence of thermal stress." (PMID 28539390, 2017). "Furthermore, its involvement in obesity resistance through regulation of metabolic genes such as PPARA and UCP1 highlight a transcriptional network focused on lipid modifiers." (PMID 28416760, 2017). "Interestingly, Mfn2 and Ucp1 show striking similarities in their effects on BAT response to cold and obesity." (PMID 28539390, 2017). "However, it is more plausible that the obesity-resistant phenotypes of these transgenic mice are due to the enhanced thermogenic ability of BAT, as it is often the case that UCP1 content is increased not only in WAT, but also in BAT, in such mouse lines." (PMID 28751675, 2017). "UCP1 induction in BAT promotes energy expenditure and protects from obesity." (PMID 28117414, 2017). "This review provides an overview of the role played by UCP1 and UCP3 in mitochondrial uncoupling/functionality as well as EM and suggests that they are a potential therapeutic target for treating obesity and its related diseases such as type II diabetes mellitus." (PMID 25713540, 2015). "Combined, our data indicate that fish oil intake enhances energy utilization by inducing UCP1 in both BAT and WAT, and could thereby prevent obesity and related metabolic disorders." (PMID 26673120, 2015). "Contrary to these findings, Oxtr−/− mice exhibited obesity with normal UCP1 expression; however, thermoregulatory ability was nonetheless compromised." (PMID 26635729, 2015). "Rhein activated uncoupling protein 1 (UCP1) expression in brown adipose tissue (BAT) in wild-type mice, suggesting that rhein may protect against obesity and related metabolic disorders through LXR antagonism and regulation of UCP1 expression in BAT." (PMID 26185519, 2015). "We focused on the UCP1-targeting miRNAs, which may indicate the process of browning WAT clearly and lay a good foundation for the prevention and treatment of obesity." (PMID 25587272, 2014). "Food intake reduction appeared to be an adaptation to 2-PCPA-induced weight loss because short-term treatment of wild type (WT) and uncoupling protein 1 (UCP1) knockout mice reduced obesity without affecting food intake." (PMID 24586592, 2014). "Irisin establishes its anti-obesity effects by imposing a BAT-like phenotype upon WAT, upregulating the ability of WAT to expend energy via enhancing mitochondrial density and increasing UCP1 expression." (PMID 24469890, 2014). "Unlike UCP1-deficient mice, UCP2 KO mice are resistant to cold exposure and they are not prone to obesity, even when fed a high fat diet, arguing against a role of UCP2 in energy expenditure." (PMID 24945157, 2014). "A later study revealed that when on a C57BL/6 background knocking out UCP-1 actually led to a paradoxical protection from diet induced obesity, which was absent at 26°C." (PMID 23504620, 2013). "Ectopic expression of Ucp1 in skeletal muscle prevents diet-induced obesity and insulin resistance in mice, and it was anticipated that lack of Ucp1 would lead to an obese phenotype." (PMID 24046387, 2013). "Our results indicated that the molecular mechanism of electroacupuncture for the treatment of obesity may be, or at least partially, through induction of both PGC-1α and UCP-1 expressions to increase energy expenditure in BAT." (PMID 24489587, 2013).